ELN (elastin)
Diseases named in the same sentence as ELN in open-access papers (continued):
Sharing a sentence is not in itself a finding about the gene and the disease.
migraine (1 paper, 2023). "An ultrastructural examination of the skin and skeletal muscle arteries of migraine patients has revealed disturbances in the extracellular matrix and an elastinopathy with dark deposits in the elastin layer." (PMID 35906498, 2023). "Other organs rich in elastin or collagen might also show changes in migraine patients." (PMID 35906498, 2023).
mineral metabolism disorders (1 paper, 2025). "Arterial stiffness is caused by dysregulation of elastin fibers and collagen, oxidative stress, mineral metabolism disorders, and low-grade inflammation, which can lead to increased myocardial preload and decreased coronary perfusion pressure." (PMID 39799348, 2025).
Morquio A Syndrome (1 paper, 2022). "This study is the first to investigate cathepsin S and elastin levels as biomarkers to assess the severity of CVD, genotype, and phenotype in Morquio A Syndrome." (PMID 35620518, 2022).
muscular dystrophy (1 paper, 2021). Muscular dystrophy (MD) refers to a group of more than 30 genetic diseases characterized by progressive weakness and degeneration of the skeletal muscles that control movement. "LOX gene is involved in fibrogenesis, as well as collagen and elastin cross-linking, it is observed that its expression level is increased in mice and dogs with muscular dystrophy, therefore, LOX, as well as ELN gene may be positively correlated with patients with BMD." (PMID 34922439, 2021).
myeloproliferative neoplasm (1 paper, 2022). A clonal hematopoietic stem cell disorder, characterized by proliferation in the bone marrow of one or more of the myeloid (i.e., granulocytic, erythroid, megakaryocytic, and mast cell) lineages. "Hematopoietic expression of JAK2V617F induced a myeloproliferative neoplasm, elastin degradation and spontaneous aortic dilation at 1 and 3 months after BMT." (PMID 36329047, 2022). "JAK2V617F mutation only in vascular cells did not induce myeloproliferative neoplasm and did not induce elastin degradation or aortic dilation." (PMID 36329047, 2022).
myxoma (1 paper, 2024). A benign soft tissue neoplasm characterized by the presence of spindle and stellate cells, lobulated growth pattern, and myxoid stroma formation. "Myxomas are usually composed of stellate or fusiform cells layered within a myxoid extracellular matrix of peptidoglycans, elastin, and collagen." (PMID 39735071, 2024).
Myxomatous mitral valve degeneration (1 paper, 2022). Myxomatous mitral valve is defined as the presence of excess leaflet tissue and leaflet thickening greater than 5 mm, resulting in a prolapse greater than 2 mm into the left atrium on parasternal long axis view. "Several studies have concentrated on the myxomatous mitral valve degeneration (MVD), which is characterized by leaflet thickening, diffuse accumulation of proteoglycan, collagen fiber disruption, and elastin fragmentation." (PMID 35902792, 2022).
Nephropathy (1 paper, 2023). A nonspecific term referring to disease or damage of the kidneys. "To the best of our knowledge, we are the first to show a direct increase in cardiac elastin protein by magnesium supplementation in rats with adenine-induced nephropathy." (PMID 36986034, 2023).
otitis media (1 paper, 2025). Inflammation of the anatomical structures of the middle ear, which is most often caused by an infectious process. "ELN gene deletion in WS reduces eustachian tube tension, impairing its opening during palatine tensor muscle contraction and hindering middle ear secretion drainage, predisposing to otitis media." (PMID 40394675, 2025).
peripheral arterial disease (1 paper, 2020). A disorder of the arteries supplying the upper and lower extremity and the visceral organs. "The association between plasma desmosines and ABI shows that elastin degradation is involved in arterial functioning and contributes to peripheral arterial disease in PXE." (PMID 32859086, 2020). "The negative association between plasma desmosines and ABI emphasizes the role of elastin degradation in peripheral arterial disease in PXE." (PMID 32859086, 2020). "Plasma desmosines and arterial calcification mass were independently inversely associated with ABI in PXE patients, which suggests that both elastin degradation and arterial calcification contribute to peripheral arterial disease in PXE." (PMID 32859086, 2020). "Since elastin fragmentation is a prominent feature of PXE, results in arterial stiffening, and is hypothesized to accelerate arterial calcification, elastin degradation might contribute to peripheral arterial disease in PXE." (PMID 32859086, 2020).
peripheral pulmonary stenosis (1 paper, 2023). "We recommend that all patients with SVAS (and/or peripheral pulmonary stenosis which does not resolve in the first couple years of life) undergo thorough genetic evaluation, including targeted testing for isolated ELN mutations." (PMID 36790509, 2023).
phlebitis (1 paper, 2023). Inflammation of a vein. "Leaflet stiffness can increase because of diseases, such as phlebitis, in which increased deposition of connective tissue components, for example, collagen and elastin, makes the leaflet more rigid leading to its dysfunction and insufficiency." (PMID 37180784, 2023).
Pleural effusion (1 paper, 2025). The presence of an excessive amount of fluid in the pleural cavity. "At the same time, ECM includes interstitial water (e.g., ascites, pleural effusions) and connective tissues such as collagen, elastin, skin, tendons, and bone." (PMID 39861464, 2025).
pneumothorax (1 paper, 2013). Abnormal presence of air in the pleural cavity. "Specifically, our discovery that certain rate kinetics of collagen-elastin dynamics may lead to unstable mechanical configurations aligns well with clinical studies, which have found that certain connective tissue diseases lead to spontaneous pneumothorax." (PMID 23762195, 2013).
posterior uveitis (1 paper, 2022). Inflammation of the choroid as well as the retina and vitreous body. "Collagen and elastin are known to be principal parts of subchoroidal tissue, tenon’s capsule, and sclera, hence, may be important intrinsic fluorophores contributing to GEFC signal in presence of choroidal thinning in retinal and choroidal lesions due to posterior uveitis." (PMID 36038591, 2022).
pressure ulcer (1 paper, 2019). "Instead, the composition of aged skin, such as its decreased collagen and elastin synthesis, would alter the material properties of its dermis, increasing vulnerability to pressure ulcer formation." (PMID 31633031, 2019).
progeria (1 paper, 2019). "Although our mechanistic experiment suggests collagen and not elastin as a causing agent of stiffness, we cannot rule out the involvement of increased medial collagen cross‐linking in vascular stiffness in progeria." (PMID 30884114, 2019).
pulmonary alveolar proteinosis (1 paper, 2023). A rare lung disorder characterized by the filling of the pulmonary alveoli with proteinaceous material which stains positive with periodic acid-Schiff stain. "pCLE technology can also be used to identify malignancy, acute rejection in lung transplantation, amiodarone lung, and pulmonary alveolar proteinosis and visualize elastin fibres in the alveolar compartment." (PMID 37584411, 2023). "In pilot studies, pCLE techniques have already been used to diagnose malignancy, acute rejection in lung transplantation, amiodarone lung, pulmonary alveolar proteinosis, and elastin fibres visible in alveolar chambers." (PMID 37584411, 2023).
pulmonary embolism (1 paper, 2024). The obstruction of the pulmonary artery or one of its branches by an embolus, sometimes associated with infarction of the lung. "The composition of clots seen in pulmonary embolism have been shown to evolve over time and have both different macro and micro appearances, with acute clots having higher fibrin content while more chronic clots consist of higher portions of collagen and elastin." (PMID 39064289, 2024).
Pulmonary hypoplasia (1 paper, 2013). "SHAM fetuses showed neither real pulmonary hypoplasia nor significant changes in elastin deposition, but sensitive qPCR could detect differences for TNC, TIMP2, and MMP2/TIMP1 ratio." (PMID 23840910, 2013).
pulmonary valve stenosis (1 paper, 2024). The pathologic narrowing of the orifice of the pulmonary valve. "Deletion of the ELN (elastin) gene in our patient correlated with the finding of pulmonary valve stenosis." (PMID 39493104, 2024).
Q fever (1 paper, 2022). A bacterial infection caused by Coxiella burnetii. "Fragmentation of elastin fibers has been described for AAAs previously; however, we found the loss of elastin fibers more evident in the lesions from Q fever AAAs than atherosclerotic AAAs." (PMID 35137689, 2022).
Renal cyst (1 paper, 2025). A fluid filled sac in the kidney. "For example, the ELN gene, expressed in large artery endothelial cells, encodes elastin, a protein crucial for vascular elasticity and associated with renal cyst progression and diabetic nephropathy." (PMID 40303495, 2025).
renal dysfunction (1 paper, 2016). "Upregulation of microfibrillar-associated protein 1, component of the elastin-associated extracellular microfibrils and fibrinogen alpha chain could contribute to deposition of extracellular insoluble fibrils, which cause progressive renal dysfunction." (PMID 27955686, 2016).
renovascular hypertension (1 paper, 2013). High blood pressure secondary to renal artery stenosis. "In a recent report, increased deposition of collagen and elastin has been reported as early as 2 weeks in aorta in renovascular hypertension." (PMID 24159376, 2013).
sarcoma (1 paper, 2023). A usually aggressive malignant neoplasm of the soft tissue or bone. "Among the matrices, the most widely used is Matrigel, a solubilized basement membrane matrix secreted by Engelbreth-Holm-Swarm mouse sarcoma cells containing laminin, collagen, elastin, entactin, fibronectin, and fibrinogen and supplemented with numerous growth factors." (PMID 36986667, 2023).
schizophrenia (1 paper, 2019). A major psychotic disorder characterized by abnormalities in the perception or expression of reality. "Our analyses placed LOX at the centre of ECM remodelling networks that are associated with BD, schizophrenia and AD, involving Elastin, which is the direct target of LOX, together with TGF-β1 and MMP9." (PMID 31477687, 2019).
scleroderma (1 paper, 2014). Scleroderma is a rare autoimmune connective tissue disorder characterized by abnormal hardening of the skin and, sometimes, other organs. "Jadassohn–Pellizzari anetoderma is characterized by a loss of dermal elastin, whereas scleroderma is characterized by the abnormal accumulation of collagen." (PMID 25075226, 2014).
sialidosis (1 paper, 2022). "In sialidosis, NEU1 deficiency and its related errors in elastin metabolism manifest typically with abnormalities that are characteristic of the early onset of sialidosis in children (such as failure to thrive, kyphosis, and facial dysmorphism)." (PMID 35847014, 2022).
Sorsby fundus dystrophy (1 paper, 2023). A rare progressive autosomal dominant macular dystrophy, presenting between the third and sixth decades of life, characterized by retinal atrophy and retinal detachment and leading to loss of central vision, then peripheral vision, and eventually blindness. "Fibulin-3 minimally interacts directly with ECM components such as elastin or fibrillin-1 however it strongly regulates TIMP-3, indicating reduction of fibulin-3 may increase aberrant elastic fiber degradation through protease/anti-protease imbalance in a similar manner to Sorsby Fundus Dystrophy." (PMID 37001705, 2023).
spinal stenosis (1 paper, 2009). Narrowing of the spinal canal. "The initial studies on the ligamentum flavum in patients with spinal stenosis revealed profound histologic changes, including hypertrophy, fibrosis and loss of elastin." (PMID 19885059, 2009). "We found that the mean grades of elastin degradation and fibrosis of the ligamentum flavum were statistically higher in the spinal stenosis samples than that in the disc herniation samples." (PMID 19885059, 2009). "We sought to further characterize these findings regarding the ligamentum by comparing the degree of elastin degradation and fibrosis in spinal stenosis patients to that of a control group of disc herniation patients." (PMID 19885059, 2009). "One of the characteristics of spinal stenosis is elastin degradation and fibrosis of the extracellular matrix of the ligamentum flavum." (PMID 19885059, 2009). "In addition, there was more severe elastin degradation and fibrosis of the ligamentum flavum in the spinal stenosis patients than that in the disc herniation patients." (PMID 19885059, 2009). "Considering the well-known ability of MMP-2 to degrade elastin, its high expression in the ligamentum flavum of spinal stenosis patients suggests that it may be, at least partially, responsible for the severe loss and disorganization of the elastin fibers observed in that pathological condition." (PMID 19885059, 2009).
staphylococcal infection (1 paper, 2021). An infection caused by Staphylococcus. "Fibronectin-binding protein A (FnBPA) mediates adhesion of S. aureus to fibrinogen, elastin and fibronectin, favoring the establishment of staphylococcal infections." (PMID 34215177, 2021).
systemic sclerosis (1 paper, 2020). A chronic disorder, possibly autoimmune, marked by excessive production of collagen which results in hardening and thickening of body tissues. "FBN2 is involved in elastic fiber formation and is abundantly present in embryonic tissues, but is also elevated along with elastin in fibrotic tissue, for instance in systemic sclerosis." (PMID 33658982, 2020).
T-cell immunodeficiency (1 paper, 2016). A broad classification of disorders that affect the cell-mediated aspect of the immune response. "Full or partial explanations for the vascular disease and T-cell immunodeficiency of SIOD patients are respectively decreased expression of elastin (ELN) in the aorta and of interleukin 7 receptor alpha chain (IL7R) in the T cells." (PMID 27816064, 2016).
Takayasu arteritis (1 paper, 2015). A rare inflammatory large-vessel vasculitis primarily affecting the aorta and its major branches, but also other large vessels, causing stenosis, occlusion, or aneurysm. "Vessel wall inflammation-targeted MRI contrast agents such as elastin-specific, collagen-specific, or macrophage-targeted agents may allow more precise evaluation of disease activity in patients with Takayasu arteritis." (PMID 26720837, 2015).
thyrotoxicosis (1 paper, 2019). A hypermetabolic syndrome caused by the elevation of thyroid hormone levels in the serum. "For instance, rats with induced thyrotoxicosis showed markers for increased oxidative stress and lipid peroxidation in addition to increased arterial stiffness, due to changes in vascular smooth muscle cell and elastin and collagen content in the vessel wall." (PMID 30859432, 2019).
tongue cancer (1 paper, 2020). A malignant neoplasm affecting the tongue. "Our RNA-Seq results revealed decreased elastin assembly and increased collagen degradation in tongue cancer tissues." (PMID 32236620, 2020).
Urethral stricture (1 paper, 2023). Narrowing of the urethra associated with inflammation or scar tissue. "Previous reports on fibrotic tissue from urethral strictures showed more elastin fibres in the fibrotic lesion proximal to the urethral obstruction compared to distal." (PMID 38032942, 2023).
Urinary incontinence (1 paper, 2023). Loss of the ability to control the urinary bladder leading to involuntary urination. "The obtained SMC population was injected into mouse models of urinary incontinence and the authors observed tissue remodeling with higher detection of elastin in the bladder." (PMID 37760170, 2023).
varicose disease (1 paper, 2025). A vascular disease characterized by the presence of enlarged and tortuous veins. "Multiple studies confirm that varicose disease promotes connective tissue matrix degradation, marked by increasing collagen content and decreasing elastin within the venous wall." (PMID 41010652, 2025).
Varicose veins (1 paper, 2012). Enlarged and tortuous veins. "Venous adventitial elastin has a critical role in regulating the venous diameter at rest, and, therefore, elastin loss may be a key factor in the development of varicose veins, preceding and precipitating dilatation." (PMID 22489273, 2012).
vascular tumors (1 paper, 2015). "AML’s are vascular tumors, composed of abnormal abundant elastin-poor vascular structures, making them prone to aneurysm and hemorrhage." (PMID 30039066, 2015).
Venous thrombosis (1 paper, 2013). Formation of a blood clot (thrombus) inside a vein, causing the obstruction of blood flow. "Chronic pulsation of the artery is thought to cause elastin, collagen deposition, and intimal fibrosis leading to formation of venous spur and venous thrombosis." (PMID 23509664, 2013).
vitamin C deficiency (1 paper, 2025). "The decrease in the expression of genes for collagen type IV and elastin in vitamin C deficiency also confirmed the close connection between vitamin C and tissue-building elements." (PMID 41228556, 2025).
vitiligo (1 paper, 2022). Generalized well circumscribed patches of leukoderma that are generally distributed over symmetric body locations and is due to autoimmune destruction of melanocytes. "Our preliminary study demonstrated that elastin fibers were decreased in vitiliginous skin, suggesting the possibility that elastin fibers are involved in vitiligo development and repigmentation." (PMID 36499690, 2022). "However, there has been little attention on the role of dermal fibers, such as collagen and elastin fibers, in the development and repigmentation of vitiligo." (PMID 36499690, 2022). "Indeed, our preliminary study demonstrated that elastin fibers were decreased in vitiliginous skin, suggesting that the elastin fiber is one of the factors involved in vitiligo development and repigmentation." (PMID 36499690, 2022).
wet age-related macular degeneration (1 paper, 2025). "Another VEGFR-targeting fusion protein composed of VEGFR1 peptide antagonist and elastin-based polypeptide inhibited VEGFA-triggered angiogenesis in vitro, and suppressed choroidal neovascularization in a wet age-related macular degeneration mouse model in vivo." (PMID 40841907, 2025).